VHL (von Hippel-Lindau tumor suppressor)
Diseases named in the same sentence as VHL in open-access papers (continued):
Sharing a sentence is not in itself a finding about the gene and the disease.
pheochromocytoma (continued). "One patient with a germline mutation in the VHL-gene (Cluster 1B), who could not be assigned to a secretion type due to missing blood values, presented with bilateral pheochromocytoma and one lymphogenic metastasis." (PMID 41276740, 2025). "We report a case of a pathogenic variant c.463+4C>G in the von Hippel-Lindau (VHL) gene identified in a patient presenting with bilateral adrenal tumors, including a histologically confirmed pheochromocytoma with no significant family history of VHL-associated tumors." (PMID 40051608, 2025). "The absence of all VHL-specific evidence in three of our patients, in contrast to the presence of pheochromocytoma in case reports, may suggest low penetrance of the variant or potential somatic allelic events causing sporadic pheochromocytoma." (PMID 40647474, 2025). "For example, type 1 VHL disease (without pheochromocytoma) is associated with mutations that cause the complete unraveling of the protein structure (missense mutations in the hydrophobic core of the VHL protein, protein-truncating mutations, and partial gene deletions)." (PMID 39272694, 2024). "However, the effect of VHL on the proteome of pheochromocytoma remains to be explored." (PMID 33828526, 2021). "Moreover, recent studies indicate that up to 25% of pheochromocytoma patients have a genetic background (NF1, VHL, SDHD, SDHB or RET gene mutations) and thus both the patients and their closest blood relatives require wide multidisciplinary diagnostics as well as long-term follow-up." (PMID 31137898, 2019). "However, the p.Arg82Leu mutation in the VHL gene described here among patients with familial bilateral pheochromocytoma, has never been reported previously in a germline configuration." (PMID 23626751, 2013). "C3orf10:VHL or BRK1:VHL (#8) - VHL is a tumour suppressor gene deleted in von Hippel Lindau disease, an autosomal dominant familial cancer syndrome that can give rise to pheochromocytoma and tumours of the kidney, central nervous system, pancreas, retina and epididymis." (PMID 22761941, 2012). "Accordingly, there has been support for the notion that both the higher RCC incidence seen with type 2B and type 1 VHL mutations and the lack of pheochromocytoma in type 1 mutants may be a result of higher HIF-α levels." (PMID 19602254, 2009). "However, germline VHL mutations that cause phaeochromocytomas and not other features of VHL disease retain the ability to regulate hypoxia-inducible factor HIF-1 and HIF-2." (PMID 15505628, 2004). "Belzutifan is a promising HIF-2α inhibitor being studied in clinical trials for pheochromocytomas and is currently the only HIF-2α inhibitor therapy approved in the United States for the treatment of patients with VHL-related tumors." (PMID 40649858, 2025). "Pheochromocytomas have the potential to be part of inherited syndromes such as MEN-2, VHL, and NF1, which implicate a variety of other pathologies and necessitate genetic screening of affected individuals and their family members." (PMID 39735644, 2024). "However, VHL‐associated pheochromocytomas do not typically express PNMT." (PMID 38747189, 2024). "Type 2B covers almost the entire spectrum of VHL manifestations including aggressive RCC, while type 2C only develops isolated pheochromocytoma." (PMID 30943211, 2019). "Notably, VHL- and SDH-mutant tumors could be distinctly subdivided into two clusters according to their mutations following genomic analysis of 202 paraganglioma and pheochromocytoma samples." (PMID 28187001, 2017). "However, it is possible that in individuals with type 1 VHL mutations, higher levels of HIF-2α and of the proapoptotic HIF target gene, EglN3, cause some culling of renal cells upon loss of the wild type allele, in a manner similar to as has been suggested for pheochromocytoma." (PMID 19602254, 2009).
pheochromocytoma (continued). "This trial is also designed to assess belzutifan efficacy on VHL-related pheochromocytomas and paragangliomas, a VHL manifestation that was not previous evaluated under belzutifan treatment." (PMID 36980625, 2023). "Metastatic pheochromocytoma occurred in 4 of 191 patients with VHL (2%), as opposed to 1 of 330 patients with MEN 2 (0.3%) (difference, 2%; 95% CI, 0%-5%; P = .06)." (PMID 31397861, 2019). "Our previous work documented vacuolated cytoplasm in SDH-mutated adenomas but not in patients with pituitary adenomas and phaeochromocytomas due to MEN1 or VHL genes." (PMID 28284009, 2017). "Unlike mutations in VHL or MEN 2 disorders, NF 1 mutations that offer an increased risk in pheochromocytoma remain to be identified." (PMID 24899893, 2014). "By contrast, type 2 mutations,which are mostly missense changes that reduce pVHL activity, predispose to theentire VHL spectrum, including pheochromocytomas with or without RCC, calledtype 2B and type 2A, respectively." (PMID 19009041, 2008). "Thus, VHL and RET appear to have only a minor role in the pathogenesis of sporadic phaeochromocytoma." (PMID 15505628, 2004). "VHL is an autosomal dominant inherited (80%) genetic condition due to an abnormal VHL gene characterized by hemangioblastomas of the brain, spinal cord, and retina; renal cysts and RCC; pheochromocytoma and paraganglioma; and pNETs with a positive family history." (PMID 38883112, 2024). "However, further research is required to determine the reasons whereby pheochromocytomas do not occur in type 1 syndrome; i.e., in the complete absence of the VHL protein." (PMID 28187001, 2017). "Pheochromocytomas in MEN2, VHL, and NF1 disorders usually are not the first clinical manifestation and are more likely to be benign and bilateral." (PMID 22953071, 2012). "We report a case of bilateral pheochromocytomas and no other VHL-related tumors in a patient with Y175C VHL and show that this mutant preserves the ability to degrade HIF in normal oxygen conditions but, similar to the wild-type VHL protein, loses its ability to degrade HIF under hypoxic conditions." (PMID 30105105, 2018).
von Hippel-Lindau disease (149 papers, 2004 to 2026). "von Hippel–Lindau disease is hereditary autosomal-dominant tumor in which carriers of disease-causing germline variant in VHL gene are at increased risk of developing benign and malignant tumors in different organs." (PMID 40620865, 2025). "Germline loss-of-function mutations in the VHL tumor suppressor gene cause von Hippel–Lindau disease, increasing the risk of hemangioblastomas, ccRCCs, and paragangliomas." (PMID 40000790, 2025). "Early clinical identification of pathogenic VHL gene variants in patients with VHL syndrome complicated by pulmonary and thyroid nodules helps in the detection and removal of tumors to prevent or reduce secondary complications." (PMID 40989257, 2025). "One of our patients carried the c.439A>G, p.I147V heterozygous mutation (rs1057517560) in the VHL gene, which causes dominantly inherited Von Hippel–Lindau Syndrome." (PMID 40650005, 2025). "The VHL-HIF-VEGF pathway is a compelling therapeutic target for both von Hippel-Lindau (VHL) syndrome and sporadic clear cell renal cell carcinoma (spRCC) patients, given the high prevalence of VHL mutations or alterations in these conditions." (PMID 40920370, 2025). "Von Hippel-Lindau (VHL) syndrome is a rare condition that is inherited in an autosomal dominant pattern and associated with germline mutations in the VHL tumour suppressor gene, leading to the development of multiple tumours." (PMID 41458790, 2025). "VHL syndrome is caused by germline mutations in the VHL gene, which encodes a protein involved in the ubiquitination and degradation of hypoxia-inducible factors (HIFs)." (PMID 40937003, 2025). "VHL gene inactivation is a hallmark of von Hippel–Lindau syndrome, a hereditary disorder predisposing patients to ccRCC and other tumors, underscoring its central role in disease pathogenesis." (PMID 41226668, 2025). "The interpretation of the germline VHL variants and the assessment of their clinical significance in VHL syndrome can be complex." (PMID 40647474, 2025). "For instance, Hereditary Breast and Ovarian Cancer (HBOC) is associated with mutations in BRCA1/2, Von Hippel-Lindau (VHL) syndrome is associated with mutations in the VHL gene, and Hereditary Retinoblastoma is associated with mutations in the RB1 gene." (PMID 40695959, 2025). "Von Hippel-Lindau (VHL) syndrome is a rare inherited genetic disorder caused by mutations in the VHL tumor suppressor gene on chromosome 3." (PMID 41458790, 2025). "VHL syndrome is a rare inherited disorder caused by mutations in the VHL gene located on chromosome 3p." (PMID 41458790, 2025). "Von Hippel–Lindau (VHL) syndrome is an autosomal dominant hereditary tumor syndrome caused by mutations in the VHL gene." (PMID 40989257, 2025). "Germline pathogenic mutations drive VHL syndrome, while in spRCC, VHL mutations or hypermethylation occur in approximately 90% of spRCC cases, leading to dysregulation of the hypoxia-inducible factor (HIF) pathway." (PMID 40920370, 2025). "The mechanism of disease in VHL syndrome is the loss of function of the VHL tumor suppressor gene, leading to the accumulation of hypoxia-inducible factors (HIFs) and the formation of highly vascularized tumors." (PMID 40647474, 2025). "The INT2GRATE|VEF requires a comprehensive assessment of the VHL zygosity, allelic disorder, and differential conditions to ensure a conservative evaluation of the germline variant associated with VHL syndrome." (PMID 40647474, 2025). "VHL syndrome, caused by germline mutations in the VHL gene, leads to inactivation of the VHL protein’s tumor-suppressive function." (PMID 41164131, 2025). "The gold standard for diagnosing von Hippel-Lindau disease is the identification of a pathogenic variant in the VHL gene, which can confirm the clinical diagnosis." (PMID 41179499, 2025).
von Hippel-Lindau disease (continued). "The observed activation of VEGF pathway is consistent with the vascular endothelial hyperplasia caused by VHL mutation in VHL syndrome and the elevated proportion of endothelial cells in this patient." (PMID 38407266, 2024). "The diagnosis of VHL syndrome is typically made with the detection of a pathogenic variant of the VHL gene or a positive family history and one VHL-associated lesion." (PMID 38975461, 2024). "Tumorigenesis in VHL syndrome is linked to the loss of function of the VHL tumor suppressor protein in cell differentiation where hypoxia-inducible factors (HIF1 and HIF2) are activated and accumulate in the cell." (PMID 39272694, 2024). "von Hippel–Lindau (VHL) syndrome is a syndrome associated with functional inactivation of the von Hippel–Lindau protein (pVHL)." (PMID 39272694, 2024). "The pathophysiology of VHL syndrome, involving the loss of function of the VHL tumor suppressor protein and subsequent activation of hypoxia-inducible factors, provides valuable insights into the molecular pathways driving tumorigenesis in this condition." (PMID 39272694, 2024). "Among all the hereditary cancer syndromes observed in renal cell carcinoma, von Hippel–Lindau disease (VHL), a VHL gene mutation likely to result in clear cell RCC (ccRCC), is the most common." (PMID 39339165, 2024). "A total of 28 germline variants were identified in the VHL gene in 34 cases affected by RH, of which 30 (88.23%) satisfied the clinical criteria for the VHL syndrome." (PMID 39336783, 2024). "Bilateral PHEOs were most frequently described in the syndromes of multiple endocrine neoplasia (MEN) type 2A and type 2B, in certain families with von Hippel–Lindau disease (VHL) or in patients with MAX and TMEM127 gene mutation." (PMID 38318817, 2024). "von Hippel-Lindau (VHL) syndrome (OMIM #193300) is an autosomal dominant disorder with incomplete penetrance occurring due to a mutation in the VHL gene present on chromosome 3." (PMID 38975461, 2024). "Von Hippel-Lindau Syndrome (VHL) is an autosomal dominant hereditary condition caused by a germline pathogenic variant in the VHL gene and characterized by the development of specific highly angiogenic benign and malignant tumors." (PMID 36980956, 2023). "Von Hippel–Lindau disease is caused by germline mutations in the VHL tumor suppressor gene, which is located on the short arm of chromosome 3 (3p25-26)." (PMID 37445575, 2023). "•The refined interpretation of germline VHL variants and phenotypical implications can aid the management of patients with suspected VHL syndrome." (PMID 35774415, 2022). "Only one case was found to be a carrier of a disease-causing variant in the VHL gene and was diagnosed with VHL syndrome (MedGen UID: 42458)." (PMID 36685941, 2022). "The histories of probands and relatives with confirmed germline VHL variants were evaluated for features of VHL syndrome." (PMID 35774415, 2022). "It has been reported that VHL-deficient mice display typical VHL syndrome, and a remarkable phenotype was impaired spermatogenesis." (PMID 35448166, 2022). "Von Hippel-Lindau disease (VHL disease or VHL syndrome) is a familial multisystem neoplastic syndrome stemming from germline disease-associated variants of the VHL tumor suppressor gene on chromosome 3." (PMID 35205407, 2022). "In fact, RSUME is able to promote SUMOylation of VHL mutated variants observed in VHL syndrome, but also abrogates HIF-2α degradation by interacting with these VHL variants in a VHL-SUMOylation independent way." (PMID 35528020, 2022).
von Hippel-Lindau disease (continued). "Von Hippel- Lindau disease is an autosomal dominantly inherited cancer syndrome in which mutations in the tumor suppressor VHL gene is believed to cause the development of characteristic tumors in the central nervous system, the eye and internal organs." (PMID 35960779, 2022). "Around 95% of patients with clinical features that meet the diagnostic criteria for von Hippel-Lindau disease (VHL) have a detectable inactivating germline variant in VHL." (PMID 35323939, 2022). "Von Hippel–Lindau disease (VHL) is an inherited cancer syndrome characterized by the loss of the VHL gene, which is a classic tumor suppressor gene." (PMID 36310638, 2022). "Von Hippel-Lindau disease (VHL) is an autosomal dominant, inherited syndrome with variants in the VHL gene causing predisposition to multi-organ benign and malignant neoplasms." (PMID 35304467, 2022). "Von Hippel-Lindau (VHL) syndrome is a hereditary systemic disease caused by a mutation in the VHL gene." (PMID 36362756, 2022). "Von Hippel-Lindau disease (VHL disease or VHL syndrome) is a familial multisystem syndrome stemming from germline disease-associated variants of the VHL tumor suppressor gene on chromosome 3." (PMID 35205407, 2022). "Collection of similar cases with detailed tumor derived somatic data can help develop a large database of VHL germline variants, that can in turn aid in more accurate clinical assessment and management for patients suspected with VHL syndrome." (PMID 35774415, 2022). "Altogether, these analyses further strengthen the clinical relevance and significance of the missense mutations in VHL gene in the familial von Hippel-Lindau disease." (PMID 35505422, 2022). "The pedigree members with confirmed germline VHL variants were evaluated for features of VHL syndrome." (PMID 35774415, 2022). "Von Hippel–Lindau (VHL) syndrome is a rare autosomal dominant disease due to a germline mutation of the VHL gene, located at chromosome 3p25-26." (PMID 34036514, 2021). "This parallels the situation in von-Hippel-Lindau disease, in which there are mutations in the VHL gene coding for the ubiquitin ligase known as VHL, again leading to constitutive activation of the HIF system." (PMID 34957538, 2021). "Mutations of VHL are also causative for the inherited autosomal dominant von Hippel–Lindau syndrome manifested by a variety of benign and malignant tumors including ccRCC." (PMID 34290272, 2021). "The VHL syndrome is caused by germline mutations of VHL gene and featured by group of multiple tumors, related to a high morbidity and mortality and exhibition of diverse phenotypes." (PMID 34923986, 2021). "Up to now, according to data from the Human Gene Mutation Database, > 500 VHL gene mutations leading to VHL syndrome have been reported." (PMID 34923986, 2021). "In case of tumor, registration and genetic monitoring should be carried out, for better constructing the family genealogical map of atypical VHL syndrome and understanding the correlation between genotype and phenotype brought by VHL mutation." (PMID 34923986, 2021). "In order to better illustrate and generalize the significance of VHL mutations in VHL syndrome or genetic pheochromocytoma and paraganglioma (PPGLs) worldwide, we screened recent literatures about VHL mutations in VHL syndrome or genetic PPGLs." (PMID 34923986, 2021). "It was suggested that VHL-loss induces formation of renal cysts which are precursor lesions that progress to clear cell renal cell carcinoma (ccRCC) in patients with von Hippel-Lindau disease." (PMID 32276433, 2020). "Hereditary retinoblastoma and hereditary renal cell carcinoma (Von-Hippel Lindau disease) arise with the inheritance of a germline loss-of-function mutation in Rb1 and VHL, respectively." (PMID 32295625, 2020). "Germline VHL mutations lead to von Hippel-Lindau disease, characterized by development of tumors in many organs, including the kidney." (PMID 32276433, 2020).